PIK3R1 (phosphoinositide-3-kinase regulatory subunit 1)
Diseases named in the same sentence as PIK3R1 in open-access papers (continued):
Sharing a sentence is not in itself a finding about the gene and the disease.
salivary gland tumors (2 papers, 2015 to 2025). "Gene mutations in the PI3K pathway (including PIK3R1) are the third most common abnormality in salivary gland tumors." (PMID 39831137, 2025). "Aberrations in the PI3K pathway (PIK3CA, PIK3R1, PTEN or AKT) were the third most common set of aberrations among all salivary gland tumors (28/117 [23.9%])." (PMID 26247885, 2015). "Importantly, aberrations in the PI3K pathway (PIK3CA, PIK3R1, PTEN or AKT) were commonly seen in salivary gland tumors (28/117 [23.9%])." (PMID 26247885, 2015).
Sepsis (2 papers, 2022 to 2023). Sepsis is defined as life-threatening organ dysfunction caused by a dysregulated host response to infection. "Additionally, the ROC diagnostic curves demonstrated that PIK3R1 was a highly significant diagnostic marker for advanced sepsis, outperforming PTEN." (PMID 37446388, 2023). "Additionally, immune infiltration analysis and ROC diagnostic curve were conducted to demonstrate the significant role of PIK3R1 in the clinical diagnosis and treatment of advanced sepsis." (PMID 37446388, 2023). "In summary, these findings suggest that prioritizing PIK3R1 as a novel target for future clinical diagnosis and treatment of advanced sepsis in combination with a ceRNA complex composed of 220 and 5100 may be beneficial." (PMID 37446388, 2023). "The results of this study indicate that 220 may act as a ceRNA complex to regulate the expression of PIK3R1, thus influencing the progression of sepsis." (PMID 37446388, 2023). "In order to ascertain the impact of PIK3R1 and PTEN on the regulation of moderate to severe sepsis occurrence and progression, the GSE54514 dataset from the GPL6947 platform in the GEO database was utilized." (PMID 37446388, 2023). "The results were particularly promising, as they revealed a significant decrease in PIK3R1 expression on the fifth day compared with the first day in non-survivors with sepsis after admission." (PMID 37446388, 2023). "Moreover, we identified that Pik3r1 and Pik3r5 were at the center of the gene co-expression network, and inhibition of PI3Kγ activity had a cardioprotective role in CLP-induced sepsis." (PMID 35721566, 2022).
stomach adenocarcinoma (2 papers, 2019 to 2025). "We analyzed mRNA expression levels of LIFR, PIK3R1 and MMP12 in cholangio carcinoma, liver hepatocellular carcinoma, pancreatic adenocarcinoma, and stomach adenocarcinoma, with the data from the TCGA." (PMID 31119098, 2019).
thrombosis (2 papers, 2019 to 2020).
uterine cancer (2 papers, 2020). Primary or metastatic malignant neoplasm involving the uterine corpus and/or the cervix. "Mutations are the most common genetic alteration in PIK3R1 and are most commonly found in uterine cancers, 30% of which have a PIK3R1 mutation." (PMID 32677674, 2020).
X-linked agammaglobulinemia (2 papers, 2020 to 2022). X-linked agammaglobulinemia (XLA) is a clinically variable form of isolated agammaglobulinemia, an inherited immunodeficiency disorder (see this term), and is characterized in affected males by recurrent bacterial infections during infancy. "Fourth, genetic mutations of non-X linked agammaglobulinemia encoding for pre-BCR and/or BCR complex (such as IGHM, CD79a, CD79b, and IGLL1 genes) and for activating mTOR signaling (such as PI3KD and PIK3R1 genes)." (PMID 33013854, 2020).
adenomyosis (1 paper, 2025). The growth of endometrial tissue inside the muscular wall of the uterine corpus. "Although mutations in FBXW7, ARHGAP35, PIK3R1, and PPP2R1A were also detected in adenomyosis, their frequencies were not higher than those in the normal endometrium." (PMID 40679511, 2025). "The mutation frequencies per subject, regardless of sampling depths, were as follows: in adenomyosis, KRAS: 33.3%, PIK3CA: 14.3%, and ARID1A: 14.3%, and in uterine endometrium, KRAS: 66.7%, PIK3CA: 57.1%, ARHGAP35: 52.4%, PPP2R1A: 33.3%, PIK3R1: 28.6%, and FGFR2: 19.0%." (PMID 40679511, 2025).
adenosarcoma (1 paper, 2017). A low grade malignant neoplasm characterized by the presence of a benign epithelial component (tubular and cleft-like glands) and a low grade sarcomatous component that contains varying amounts of fibrous and smooth muscle tissues. "In our cohort of adenosarcomas, we detected alterations in PI3K pathway in 26% (5/19) of cases (PIK3CA, PIK3CG, PIK3R1, PTEN mutations and/or amplification of AKT2 or ERBB3)." (PMID 28267263, 2017).
allergic rhinitis (1 paper, 2023). Inflammation of the nasal mucous membranes caused by an IgE-mediated response to external allergens. "In view of tumors and allergic rhinitis both involve complex immune regulatory systems, these results indicate that PIK3R1 may be an important target of AIT of AR." (PMID 37430199, 2023).
anaplastic oligodendroglioma (1 paper, 2023). A WHO grade III oligodendroglioma with focal or diffuse malignant morphologic features (prominent nuclear pleomorphism, mitoses, and increased cellularity). "The pathological diagnosis was anaplastic oligodendroglioma (WHO grade III), with IDH1:p.R132H, PIK3R1:p.G376R, CIC:p.N205S, and FUBP1:p.Y505Gfs*16 mutations confirmed as driver genes in tumor tissue." (PMID 37533228, 2023).
Ataxia (1 paper, 2020). Ataxia refers to impaired coordination of voluntary muscle movement. "More specifically, the PIK3R1 gene was under-expressed in neuronal datasets as well as in fibroblasts and peripheral blood, while AKT2, PPP2R5C, and SPTLC1 were found over-expressed in neuronal and fibroblast datasets of the “ataxia” phenotype." (PMID 32937819, 2020).
bladder tumours (1 paper, 2013). "Mutations in PIK3R1 identified in bladder tumours and cell lines." (PMID 24367658, 2013). "In a panel of 44 bladder tumour cell lines, 80% had reduced PIK3R1 mRNA expression relative to normal urothelial cells." (PMID 24367658, 2013).
Brain Malformation (1 paper, 2024). "Gene-specific recommendations were recently reported for PIK3R1, and for AKT3, MTOR, PIK3CA and PIK3R2 by the ClinGen Brain Malformation Variant Curation Expert Panel." (PMID 38778413, 2024).
Cachexia (1 paper, 2024). Severe weight loss, wasting of muscle, loss of appetite, and general debility related to a chronic disease. "Notably, expression of genes involved in the regulation of metabolic activities, including Pik3r1, Pdk4, Foxo1, Rorc and Lpin1, increased in type IIb myonuclei upon cachexia." (PMID 39001644, 2024).
cholangiocarcinoma (1 paper, 2019). A carcinoma that arises from the intrahepatic biliary tree (intrahepatic cholangiocarcinoma) or from the junction, or adjacent to the junction, of the right and left hepatic ducts (hilar cholangiocarcinoma). "Furthermore, in HuH28 human cholangiocarcinoma cells' research, Okamoto and colleagues found miR-221 could target phosphoinositide-3-kinase, regulatory subunit 1 (PIK3R1), to inhibit HuH28 cell proliferation and conferred Gem sensitivity." (PMID 31929798, 2019).
colitis (1 paper, 2025). Inflammation of the colon. "The active ingredients may act on 352 core protein targets, including EGFR, AKT1, PIK3R1, PIK3CB, and MAPK1, thereby modulating relevant pathways, such as MAPK and PI3K-Akt signaling pathways, and thus alleviating inflammation and intestinal damage in colitis." (PMID 40365509, 2025).
colorectal tumors (1 paper, 2020). "This miRNA is frequently downregulated in colorectal tumors and acts predominantly as a tumor suppressor element by targeting phosphoinositide-3-kinase regulatory subunit 1 (PIK3R1) and Runt-related transcription factor 2 (RUNX2), both crucial for the development of tumors." (PMID 32083000, 2020).
congenital toxoplasmosis (1 paper, 2019). Toxoplasma infection that is present from birth. "We have described two patients, a mother and daughter, with an essential donor splice site mutation of PIK3R1 and disseminated and congenital toxoplasmosis, respectively." (PMID 30891027, 2019).
Cowden syndrome (1 paper, 2024). "Some other drug candidates targeting proteins encoded by BCC-associated loci are also currently under consideration in ongoing clinical trials for treating various cancer types and Cowden syndrome, including samotolisib, a PI3-kinase class I inhibitor targeting PIK3R1." (PMID 38182794, 2024).
developmental delays (1 paper, 2025). "Neurological symptoms linked to PIK3R1 mutations have also been reported, including developmental delays, seizures, and, more recently, secondary microcephaly." (PMID 40568112, 2025).
diabetic cardiomyopathy (1 paper, 2021). Diabetic cardiomyopathy is a disorder of the heart muscle in people with diabetes. "In this study, PIK3R1 may also play a critical role in AMI progression in patients with DM, which may serve as a novel biomarker and therapeutic target for diabetic cardiomyopathy." (PMID 34887920, 2021).
diffuse astrocytoma (1 paper, 2020). A low-grade (WHO grade II) astrocytic neoplasm. "Attempts to molecularly define the aggressive type of diffuse astrocytomas have suggested several genetic markers such as RB1 pathway alterations (e.g., CDKN2A/B homozygous deletion or CDK4 amplification), PIK3R1 mutation, PDGFRA amplification, or G-CIMP low type in the methylation cluster." (PMID 33228806, 2020).
endometrial endometrioid adenocarcinoma (1 paper, 2023). A primary endometrial adenocarcinoma composed of neoplastic cells that form complex glandular patterns associated with budding and branching of the neoplastic glands. "The results showed that both PIK3CA mutations and PIK3R1 mutations were associated with endometrial endometrioid adenocarcinoma (EEA), compared with serous endometrioid adenocarcinoma (SEA) (OR = 1.9, 5.2 and p = 0.03, 0.00)." (PMID 37340596, 2023).
endometrioid endometrial carcinoma (1 paper, 2022).
endometrioid tumor (1 paper, 2025). A benign, borderline, or malignant epithelial tumor of the female reproductive system characterized by the presence of glands and/or cysts lined by neoplastic cells that resemble endometrial cells. "In detail, two endometrioid tumors with a PIK3R1 mutation had a coexisting PTEN mutation, and one of them also had a mutation in the KRAS gene." (PMID 39858051, 2025). "Because KRAS mutations can stimulate PI3K activity and were observed in 16% (4/25) of endometrioid tumors, the frequency of the PI3K pathway aberration due to PIK3R1, PIK3CA, PTEN, and KRAS mutations may increase to 60% (15/25) in this histotype." (PMID 39858051, 2025).
Ewing sarcoma (1 paper, 2023). A small round cell tumor that lacks morphologic, immunohistochemical, and electron microscopic evidence of neuroectodermal differentiation. "Moreover, some studies have also indicated that PIK3R1, NOTCH1, and CREBBP are common in recurrent Ewing sarcoma." (PMID 36964542, 2023).
fallopian tube carcinoma (1 paper, 2024). A carcinoma that arises from epithelial cells of the fallopian tube. "A report at the 2016 ASCO meeting showed a cohort of 379 patients with ovarian or fallopian tube carcinoma have been evaluated for 10 genes AKT1, AKT2, AKT3, mTOR, PIK3CA, PIK3C2B, PIK3R1, PTEN, TSC1, TSC2 in the PI3K/AKT/mTOR pathway." (PMID 38167649, 2024).
gall bladder carcinoma (1 paper, 2021). "A study was carried out to identify the expression of LIFR, PIK3R1, and MMP- 12 in gall bladder carcinoma." (PMID 33892690, 2021).
giant cell glioblastoma (1 paper, 2023).
gliosarcoma (1 paper, 2019). A rare histological variant of glioblastoma (WHO grade IV) characterized by a biphasic tissue pattern with alternating areas displaying glial and mesenchymal differentiation (WHO). "We found frequent alterations in PIK3 genes in 3/10 gliosarcoma specimens, with the PIK3CA gene being mutated twice in one gliosarcoma and the PIK3R1 gene harboring indel-events in two samples." (PMID 30818875, 2019). "We found frequent alterations in PIK3 genes in 4/10 gliosarcoma specimens, with the PIK3CA gene being mutated twice in one sample and the PIK3R1 gene harboring the indel in two samples." (PMID 30818875, 2019). "Somatic coding indels in NF1 (3/10 gliosarcoma samples), PTEN (2/10), RB1 (2/10) and PIK3R1 (2/10) genes with a minimal penetration of 15% (within a given sample) were found in 5/10 samples." (PMID 30818875, 2019).
heart tumors (1 paper, 2024).
Herpesvirus Infections (1 paper, 2018). "Since these two papers were published, additional papers have reported persistent EBV or CMV viremia or severe herpesvirus infections in patients with gain-of-function mutations in PIK3R1." (PMID 29599765, 2018).
hypersplenism (1 paper, 2021). Overactive functioning of the spleen, resulting in excessive destruction of blood cells. "Knockdown of Pik3r1 reportedly inhibits the activity of splenic macrophages associated with hypersplenism." (PMID 33628784, 2021).
hypertriglyceridemia (1 paper, 2021). A laboratory test result indicating elevated triglyceride concentration in the blood. "The elimination of PIK3R1 in white adipose tissue impairs the glucocorticoids’ ability to stimulate lipolysis, resulting in hypertriglyceridemia and fatty liver." (PMID 34827785, 2021).
immunotoxicity (1 paper, 2025). "Notably, 44 targets, including EGFR, AKT1, PIK3R1, PTEN, and mTOR, were mapped to the PI3K-Akt signaling pathway, highlighting its potential association with celastrol-induced immunotoxicity." (PMID 40495892, 2025).
Infertility (1 paper, 2023). "By analyzing DEGs, molecular docking and ADMET properties, we suggest that identified hub proteins, especially VEGFA and PIK3R1 can be used as a target to treat infertility mediated cancer progression." (PMID 36608061, 2023). "So, PIK3R1 maybe act as a therapeutic target for infertility and infertility-related cancer." (PMID 36608061, 2023). "Molecular docking and ADMET properties against VEGFA (PDB ID: 1FLT) and PIK3R1 (PDB ID: 5M6U) showed sesamin, galangin, and coumestrol were the top three compounds that might play a role on therapeutic target in the treatment of infertility and infertility mediated cancer progression." (PMID 36608061, 2023).
invasive ductal carcinoma of the breast (1 paper, 2024). "In invasive ductal carcinoma of the breast, PIK3R1 is among the genes identified as differentially expressed when compared to normal tissue." (PMID 39850811, 2024).
ischemia (1 paper, 2022). A hypoperfusion of the BLOOD through an organ or tissue caused by a PATHOLOGIC CONSTRICTION or obstruction of its BLOOD VESSELS, or an absence of BLOOD CIRCULATION. "There were 10 active constituents against ICVD, including quercetin, luteolin, kaempferol, and naringenin, and 10 important targets for anticerebral ischemia, namely, PIK3CA, APP, PIK3R1, MAPK1, MAPK3, AKT1, PRKCD, Fyn, RAC1, and NF-κB1." (PMID 35432563, 2022).
kidney damage (1 paper, 2025). "Another powerful therapeutic target in the development of kidney damage is the signal transducer and activator of transcription 3 (STAT3)/PIK3R1/mechanistic target of rapamycin (mTOR) axis." (PMID 41318413, 2025).
lymphatic malformation (1 paper, 2024). Primary lymphedema is caused by anatomic or functional defects in the lymphatic system, resulting in chronic swelling of body parts and lymphatic-system malformation. "We identified somatic variants within 26 of 44 (59%) individuals with slow-flow anomalies (either lymphatic malformation, venous malformation (VM), or mixed lymphatic/venous malformations) within the genes PIK3CA, TEK, GNAQ, BRAF, GNA11, and PIK3R1 with VAFs ranging between 0.7% to 24.8%." (PMID 39669602, 2024).
Merkel cell carcinomas (1 paper, 2016). "Importantly, aberrations in the PI3K/AKT/mTOR pathway (AKT2, FBXW7, NF1, PIK3CA, PIK3R1, PTEN or RICTOR) were also commonly seen in Merkel cell carcinomas (9/17 [53%])." (PMID 26981779, 2016).
metastatic cancer (1 paper, 2018). A carcinoma which has spread from the original site of growth to another anatomic site. "Mice with a liver-specific deletion of Pik3r1(-/-), the gene encoding p85α, not only showed decreased PTEN activity, elevated PI3,4,5P3 levels and increased Akt activation, they also developed liver tumors which progressed to metastatic cancer." (PMID 30651929, 2018).
myeloid neoplasm (1 paper, 2020). Proliferation of myeloid cells originating from a primitive stem cell. "Of the two tumors with dual FGFR1 + PIK3R1 mutations, one contained an accompanying PTPN11 mutation (p.A72T), which is a known mutational hotspot in myeloid neoplasms thus providing support for pathogenicity [Catalog of Somatic Mutations in Cancer database v91 release]." (PMID 32859279, 2020).
myopia (1 paper, 2023). "The 6 important intersectional targets of DZP for myopia treatment were STAT3, PIK3CA, PIK3R1, MAPK1, MAPK3, and HSP90AA1." (PMID 37747014, 2023).
neuroepithelial tumors (1 paper, 2025). "In our study, pathogenic variants in FGFR1 and PIK3R1 were identified in two patients with neuroepithelial tumors, with VAFs ranging from 24–36%." (PMID 39859528, 2025).
ocular hypotension (1 paper, 2024). Abnormally low intraocular pressure often related to chronic inflammation (uveitis). "Short stature, joint hyperextension, ocular hypotension, Rieger abnormalities, and delayed tooth eruption (SHORT) syndrom is a rare primary autosomal dominant genetic disorder mainly caused by pathogenic loss-of-function variants in the phosphoinositide-3-kinase regulatory subunit 1 (PIK3R1) gene." (PMID 39735640, 2024).
oesophageal cancers (1 paper, 2025). "As biomarkers, in oesophageal cancers, previous studies have detected 19/29 (65.5%) PIK3R1-positive cancers and considerable variation in constitutively activated AKT (25–90%) in cancer tissues compared with normal tissue." (PMID 40615716, 2025).
periodontal disease (1 paper, 2024). "An overexpression of CTNNB1, FOS, JUN, GRB2, PIK3CA, and PIK3R1 may affect the cell cycle, resulting in excessive cell proliferation, and malignant transformation, besides being related to periodontal disease development and progression." (PMID 39517401, 2024).
periodontitis (1 paper, 2020). An acute or chronic inflammatory process that affects the tissues that surround and support the teeth. "Notably, four of the cluster A genes, specifically, CBL, GRB2, PIK3R1, and RELA, were also ranked among the five leader genes previously identified in periodontitis." (PMID 32962181, 2020).